SNORD14A (small nucleolar RNA, C/D box 14A)
Synonyms: U14; RNU14A; RNU14; U14-S13-5
Gene: Small nucleolar RNA gene on chromosome 11 (17,074,654 to 17,074,744, reverse strand). Ensembl gene ENSG00000272034.
Gene Ontology:
Biological process: RNA processing
Cellular component: nucleolus
Homologues: Orthologues: macaque SNORD14 (97% identical), pig SNORD14 (95% identical), guinea pig SNORD14A (88% identical), tropical clawed frog SNORD14 (80% identical). Paralogues in human: SNORD14B (82% identical), SNORD14E (75% identical), SNORD14 (74% identical), SNORD14C (74% identical), SNORD14D (68% identical).